NTSR1 (neurotensin receptor 1)
Diseases named in the same sentence as NTSR1 in open-access papers (continued):
Sharing a sentence is not in itself a finding about the gene and the disease.
colon carcinoma (7 papers, 2009 to 2021). "NTSR1 acts like an oncogene in many cancers, but its hypermethylation in colon tumors suggests a role as a tumor suppressor as well." (PMID 34680073, 2021). "NTS appears to promote cell growth in CHO cells transformed with human NTSR1 and in colon cancer HT29 cells." (PMID 31093954, 2019). "In inflammatory bowel disease- (IBD-) related colon cancers, NTSR1 appears to be a β-catenin inducible gene." (PMID 28316623, 2017). "Moreover, NTSR1 expression on colon cancer cells appears to be upregulated by the Wnt/APC (adenomatous polyposis coli) signalling pathway, a well-known carcinogenesis pathway in CRC." (PMID 28316623, 2017). "Therefore, NTS/NTSR1 may be a potential target for preventive or therapeutic strategies in colon cancer." (PMID 28316623, 2017). "NTSR1 and NTSR3 forms a heterodimer on the surface of colon cancer cells." (PMID 32764278, 2020). "NTSR1 and NTSR3 exist as a heterodimer on the cell surface of HT29 human colon cancer cells." (PMID 28316623, 2017). "Although NTSR1 was not normally detectable on human colonic epithelial cells, it appeared to be expressed as ectopic receptors in human colon cancer cells." (PMID 28316623, 2017). "NTSR1 appears to be solely expressed in colonic cancer cells but not in normal colon cells." (PMID 31093954, 2019).
glioblastoma (7 papers, 2015 to 2024). The most malignant astrocytic tumor (WHO grade IV). "Interfering with NTSR1 expression causes anti-invasive effects through the Jun/miR-494/SOCS6 axis in glioblastoma cells." (PMID 36439693, 2022). "Ntsr1 has been reported to be upregulated by Wnt in glioblastoma, which contrasts with its downregulation in the fetal kidney shown in this study, indicating context-dependent regulation." (PMID 39310276, 2024). "In glioblastoma cells, NTSR1 expression is increased by the Wnt pathway activator Wnt3a and decreased by the Wnt inhibitor iCRT3." (PMID 39310276, 2024). "Interfering with NTSR1 expression exhibits anti-invasive effects through the Jun/miR-494/SOCS6 axis in glioblastoma cells." (PMID 36439693, 2022). "For example, NTSR1 inhibition induces intrinsic apoptosis via downregulation of Bcl-w and Bcl-2 in glioblastoma cells." (PMID 34439758, 2021). "NTSR1 and Wnt/β-catenin enhance tumor growth in glioblastoma." (PMID 36439693, 2022). "NTS and NTSR1 showed high levels of expression, particularly in the glioblastoma (GBM) samples." (PMID 25644759, 2015).
schizophrenia (7 papers, 2011 to 2023). A major psychotic disorder characterized by abnormalities in the perception or expression of reality. "Loss of NTSR1 function established a role in dopaminergic reward, managing features associated with schizophrenia, and established a lack of involvement in analgesia which is mediated through NTSR2." (PMID 36523815, 2022). "Our results suggested that the NTSR1 gene was associated with this significant endophenotype of schizophrenia, and raised the possibility that we can take into account of this information for schizophrenia diagnosis." (PMID 21394204, 2011). "In the CNS, NT exerts various effects, including analgesia and central control of blood pressure, is involved in the pathophysiology of schizophrenia and Parkinson’s disease, with levels of endogenous NT and NTSR1 expression decreased in patients with the symptoms of schizophrenia." (PMID 35198603, 2022). "Direct observation of NTSR1-Venus will enable future studies to examine NTSR1’s neuromodulation of dopamine and signaling properties at receptor level and may contribute to drug discovery efforts in Parkinson’s disease, schizophrenia and addiction." (PMID 36523815, 2022). "Previous studies have shown an important role for NT and NTSR1 in schizophrenia." (PMID 21394204, 2011). "In terms of the NTSR1 gene, one previous study reported that NTSR1 gene polymorphism was associated with schizophrenia, although two later studies did not replicate this result." (PMID 21394204, 2011). "The neurotensin receptor 1 (NTS1) is a G protein-coupled receptor (GPCR) with promise as a drug target for the treatment of pain, schizophrenia, obesity, addiction, and various cancers." (PMID 37286565, 2023). "For example, TH was related to essential hypertension; DRD2 to childhood temperament, extraversion, and antisocial behavior; and neurotensin genes (NLN, NTSR1, NTRS2) to schizophrenia and memory consolidation." (PMID 26308205, 2015).
adenoma (6 papers, 2015 to 2023). A neoplasm arising from the epithelium. "The progression from early adenoma to invasive carcinoma is associated with an increase of nuclear β-catenin levels, which could promote transcriptional activity at NTSR1 that prevents the NTSR1 promoter from being methylated in advanced tumors." (PMID 26334593, 2015). "In LS, NTSR1 had significantly increased methylation values in tumor samples compared to normal counterparts, both in adenomas (p < 0.001) and carcinomas (p = 0.003)." (PMID 34680073, 2021). "Whilst NTSR1 mRNA expression was undetectable in differentiated epithelial cells of normal colonic epithelium, it was expressed at a moderate level in adenomas and adenocarcinomas." (PMID 28316623, 2017). "In colorectal lesions that contain both adenoma and carcinoma components, we often observed NTSR1 hypermethylation in the adenomatous portion and generally lower methylation levels in the cancerous portions." (PMID 26334593, 2015). "Additionally, there is incremental levels of NTSR1 mRNA expression in normal colonic epithelium, adenomas, and adenocarcinoma." (PMID 32764278, 2020). "Furthermore, NTSR1 mRNA expression increased as colonic epithelial cells progressed along the adenoma to adenocarcinoma pathway; infiltrating margins and tissue from LVI showed highest intensity of NTSR1 expression." (PMID 32764278, 2020). "In vivo, NTSR1 mRNA expression was undetectable in superficial differentiated epithelial cells in histological specimens of normal human colonic epithelium, but there was moderate and strong expression in adenomas and adenocarcinomas respectively." (PMID 31093954, 2019). "Further analysis of NTSR1 methylation in additional mixed colorectal lesions containing adenomatous and malignant portions (n = 22) showed that methylation levels were significantly higher in the adenomas than adjacent normal colonic tissue, but they were generally lower in the malignant portions." (PMID 26334593, 2015). "NTSR1 and PTGS2 hypermethylation were elevated already in adenomas and the latter one showed an even somewhat higher hypermethylation frequency in adenomas compared to carcinomas, 50% vs. 33%." (PMID 34680073, 2021). "NTSR1 mRNA expression was found to be non-detectable in epithelial cells of normal colonic epithelium but adenomas and adenocarcinomas demonstrated moderate to strong expression (p < 0.05)." (PMID 31093954, 2019).
ductal pancreatic adenocarcinoma (6 papers, 2011 to 2025). "High NTSR1 expression is associated with pancreatic ductal adenocarcinoma and is a poor prognosis factor." (PMID 30965637, 2019). "NTSR1 in vivo imaging has already been successfully used in patients with ductal pancreatic adenocarcinoma." (PMID 21364741, 2011). "Remarkably, NTSR1 is highly expressed on 75% of pancreatic ductal adenocarcinomas (PDACs)." (PMID 40574013, 2025). "In particular, NTSR1 is overexpressed in at least 75% of pancreatic ductal adenocarcinomas." (PMID 40574013, 2025).
Obesity (6 papers, 2015 to 2025). Accumulation of substantial excess body fat. "Lastly, we examined whether deletion of NtsR1 from adult VTA DA neurons impacts the susceptibility to develop diet-induced obesity." (PMID 36213756, 2022). "It is possible that enhanced DA system hyperactivity in developmental deleted NtsR1 mice was offset by obesity, which can blunt the DA system." (PMID 36213756, 2022). "Overall, these data support that Cre-lox mediated adult-onset deletion of NtsR1 from VTA DA neurons modestly protects mice from diet-induced obesity and hunger-mediated feeding." (PMID 36213756, 2022). "Indeed, brain permeable NtsR-1-specific agonists decrease feeding and body weight in normal mice, as well as in leptin-deficient obese mice, suggesting that Nts action via NtsR-1 may be useful in treating obesity." (PMID 25741247, 2015). "In our current study, we utilized novel IEC monolayers and organoid ex vivo models derived from mice, including Nts- and Ntsr1-deficient mice, as well as human tissue to demonstrate that NTS contributes to impaired AMPK signaling in IECs associated with HFD-induced obesity." (PMID 40451927, 2025). "In this study we examined whether NtsR1 expression in DA neurons is necessary for energy balance in the face of normal and obesity-promoting diets." (PMID 36213756, 2022). "Taken together, developmental loss of NtsR1 from DA neurons protects from obesity via yet unknown mechanisms independent of feeding and locomotor activity, while loss of NtsR1 expression from adult VTA DA neurons also impedes normal coordination of energy status and feeding." (PMID 36213756, 2022). "Our data show that developmental deletion of NtsR1 from DA neurons has little impact on normal body weight but is protective in the face of diet-induced obesity, though this is not attributable to alterations in feeding or energy expenditure." (PMID 36213756, 2022). "Developmental deletion of NtsR1 from DA neurons protected mice from diet-induced obesity, but not via altering feeding, physical activity, or energy expenditure." (PMID 36213756, 2022). "Intriguingly, the leptin/NtsR-1 system may have more impact in regulating non-homeostatic feeding: while mice lacking NtsR1 exhibit normal chow intake, they over consume palatable, high-fat diet or a sucrose solution that promotes obesity." (PMID 25741247, 2015).
gastric cancer (5 papers, 2020 to 2024). A primary or metastatic malignant neoplasm involving the stomach. "Furthermore, depleting NTSR1 through the Erk signaling pathway decreased the invasion and migration of gastric cancer cells by confirmation of NT-induced metastasis through observing changes in epithelial–mesenchymal transition markers." (PMID 39409942, 2024). "The authors felt this was compelling evidence that NTSR1 could be a therapeutic target for gastric cancers." (PMID 32764278, 2020). "The expression of MMP‐9 was upregulated in Panc‐1‐3P cells and NTSR1‐overexpressing SUIT‐2 cells, which was in accordance with a previous report in gastric cancer cells." (PMID 33034134, 2021). "In vitro tests demonstrated that NTSR1 mRNA levels in gastric cancer tissues and cell lines were higher than those in non-cancerous tissues and other cancer cell lines." (PMID 39409942, 2024). "NTSR1 mRNA expression was higher in gastric cancers compared to non-cancerous tissue." (PMID 32764278, 2020).
breast tumors (4 papers, 2009 to 2025). "Neurotensin receptor 1 has been observed in the cytoplasm or nucleus of primary breast tumors, and it seems that this distribution is mutually exclusive." (PMID 41301028, 2025). "The activation of HER2-3 and EGFR by the neurotensin/neurotensin receptor 1 system renders breast tumors aggressive, and the administration of neurotensin receptor 1 antagonists blocked the adherence and migration/invasion of BC cells." (PMID 41301028, 2025). "From 1419 primary breast tumors in a French institute, neurotensin receptor-1 overexpression was found in about one-third of breast tumors from patients undergoing primary surgery." (PMID 36650218, 2023). "Together with the expression of NTSR1, these data validate our hypothesis of the NTS paracrine regulation of transformed epithelial cells during the neoplastic process, with NTS released from the surrounding normal breast tissue or from the breast tumor." (PMID 19156213, 2009).
colorectal tumors (4 papers, 2015 to 2022). "We next assessed the association between NTSR1 methylation and other molecular and clinicopathological features of colorectal tumors." (PMID 26334593, 2015). "In conclusion, we found that NTSR1 is frequently methylated in colorectal tumors and that elevated levels of NTSR1 methylation are associated with laterally spreading and noninvasive growth patterns." (PMID 26334593, 2015). "Because expression of NTSR1 is reportedly upregulated in various malignancies, we also determined whether any chromosomal aberrations were associated with NTSR1 in colorectal tumors." (PMID 26334593, 2015). "We show that methylation-associated silencing of NTSR1 is inversely associated with the invasiveness of colorectal tumors, and that its methylation could be a predictive biomarker of a better prognosis in CRC patients." (PMID 26334593, 2015). "Furthermore, NTSR1 methylation is linked to the lateral and noninvasive progression of colorectal tumors, whereas lowered levels of methylation might enhance the malignant potential via activation of NTSR1." (PMID 36439693, 2022). "They found that whereas noninvasive colorectal tumours tended to express high levels of hypermethylated NTSR1, invasive CRC tended to have unmethylated NTSR1." (PMID 28316623, 2017). "We identified a number of CpG islands differentially methylated between the two groups, including that of NTSR1, which was preferentially methylated in laterally growing and noninvasive colorectal tumors." (PMID 26334593, 2015). "Quantitative bisulfite pyrosequencing revealed that NTSR1 is frequently methylated in colorectal tumors, with large NTs exhibiting the highest methylation levels." (PMID 26334593, 2015). "The results summarized above suggest NTSR1 is a target of epigenetic silencing in colorectal tumors, despite it functions as an oncogene." (PMID 26334593, 2015). "Given the apparent oncogenic function of NTSR1, it seems paradoxical that NTSR1 would be a target of aberrant DNA methylation in colorectal tumors." (PMID 26334593, 2015). "Recent analysis of primary colorectal tumours, including adenomatous and malignant portion of tumours, revealed that neurotensin receptor 1 (NTSR1), which is closely related to NMURs, was frequently methylated in the adenomatous portion, while methylation levels were lower in the cancerous portion." (PMID 34493299, 2021). "Because differences in NMUR expression were observed, we determined whether NMUR expression is regulated at the transcriptional level, as shown for neurotensin receptor 1 (NTSR1), a receptor subtype closely related to NMURs, in primary colorectal tumours." (PMID 34493299, 2021). "Among these, we focused on neurotensin receptor 1 (NTSR1) because although neurotensin (NTS) signaling has been strongly implicated in tumorigenesis, methylation of NTSR1 has not yet been reported in colorectal tumors." (PMID 26334593, 2015).
non-small cell lung carcinoma (4 papers, 2015 to 2025). A group of at least three distinct histological types of lung cancer, including non-small cell squamous cell carcinoma, adenocarcinoma, and large cell carcinoma. "Reverse transcriptase PCR was used to confirm the expression of NTSR1 in two non-small cell lung cancer cells: A549 and H23 to ensure that these cells actually express the receptor." (PMID 26410728, 2015). "NTSR1 is upregulated in multiple types of cancer, including non-small cell lung cancer (NSCLC), but not in normal tissues." (PMID 40133959, 2025).
colonic adenocarcinomas (3 papers, 2016 to 2019). "This further supports that increased NTSR1 expression may be an early event during colonic tumourigenesis and also contributes to tumour progression and aggressive behaviour in colonic adenocarcinomas." (PMID 28316623, 2017).
hepatocellular carcinoma (3 papers, 2015 to 2022). A malignant tumor that arises from hepatocytes. "The overexpression of NTSR1 has been shown to indicate poor survival of patients with hepatocellular carcinoma and result in the activation of EGFR." (PMID 35251577, 2022).
inflammatory bowel disease (3 papers, 2015 to 2025). A spectrum of small and large bowel inflammatory diseases of unknown etiology. "Studies have linked NTSR1 overexpression to inflammatory bowel disease progression and neuroinflammatory responses, suggesting a potential role in inflammatory conditions like sepsis." (PMID 40756031, 2025). "Overexpression of NTSR1 is also observed during the progression of inflammatory bowel disease-related oncogenesis." (PMID 26334593, 2015).
invasive ductal breast carcinoma (3 papers, 2009 to 2022). The most common type of invasive breast carcinoma, accounting for approximately 70% of breast carcinomas. "It was reported that 91% of invasive ductal breast carcinoma specimens expressed NTSR1, and NTSR1 was involved in cellular migration, invasion, and the induction of matrix metalloproteases-9." (PMID 36294386, 2022). "we investigated the expression of NTS and NTSR1 in normal human breast tissue and in invasive ductal breast carcinomas (IDCs) by immunohistochemistry and RT-PCR." (PMID 19156213, 2009).
neuroblastoma (3 papers, 2014 to 2021). Neuroblastoma (NB) is the most common solid, extracranial childhood tumor. "Exposure to an NT analog leads to destabilization of Ntsr1 mRNA in mouse neuroblastoma and HT-29 cells." (PMID 24416154, 2014). "Interestingly, NTSR1 internalization, which is overactive in cancer cells, has become an efficient pathway to introduce therapeutic genes that are intravenously delivered by the NTS-polyplex nanoparticles as we previously demonstrated in a murine neuroblastoma model." (PMID 24824754, 2014). "The absence of apoptosis in the liver, lungs and kidneys is consistent with previous findings in a neuroblastoma mouse model and can be explained by the inability of NTS-polyplex nanoparticles to transfect tissues lacking NTSR1." (PMID 24824754, 2014).
Alzheimer disease (2 papers, 2013 to 2019). A progressive, neurodegenerative disease characterized by loss of function and death of nerve cells in several areas of the brain leading to loss of cognitive function such as memory and language. "It is also described that activation of neurotensin receptor 1 has beneficial actions in a mouse model of Alzheimer's disease." (PMID 31036753, 2019). "In the temporal lobe of Alzheimer’s disease (AD) patients, the expression levels of both NTSR1 and NTSR2 were profoundly decreased in AD, whereas the expression of NT was slightly reduced, and the level of NTSR3/sortilin did not vary." (PMID 24709648, 2013).
Arthritis (2 papers, 2012 to 2024). Inflammation of a joint. "Ntsr1-deficient mice developed serum-transferred arthritis equivalent to that of controls." (PMID 22314006, 2012). "We further have shown that the only other reported functional NMU receptor, a heterodimer of NTSR1 and the growth hormone secretagogue receptor 1 b, was also dispensable for the development of serum-transferred arthritis." (PMID 22314006, 2012).
depression (2 papers, 2014 to 2024). "The MS-induced alternations of DNA methylation in the promoter region of NTSR1 in the amygdala may be associated with vulnerability to the development of anxiety disorders and depression in adulthood." (PMID 24831231, 2014). "NTSR1 and NTSR3 are primarily implicated in depression, while NTSR2 and secondarily NTSR1 in PTSD." (PMID 37534788, 2024). "Because ELS plays an important role in the clinical vulnerability to the development of anxiety disorders and depression in adulthood, our results suggest the hypothesis that manipulating the NTSR1 gene in AMY may have a therapeutic action to improve from these diseases." (PMID 24831231, 2014). "Depression occurring after stroke, or post-stroke depression (PSD), was also shown to be attenuated by an NTSR1 agonist." (PMID 37534788, 2024).
gastrointestinal stromal tumor (2 papers, 2011 to 2020). "NTSR1 expression was also elevated in human gastrointestinal stromal tumours." (PMID 32764278, 2020).